Y_RNA (Y RNA )
Gene: Miscellaneous RNA gene on chromosome 5 (108,891,437 to 108,891,546, forward strand). Ensembl gene ENSG00000207404.
Homologues: Orthologues: chimpanzee Y_RNA (97% identical), macaque Y_RNA (92% identical). Paralogues in human: RNY1 (90% identical), Y_RNA (89% identical), Y_RNA (88% identical), Y_RNA (87% identical), Y_RNA (86% identical), RNY1P11 (85% identical), Y_RNA (85% identical), RNY1P8 (84% identical), Y_RNA (84% identical), RNY1P5 (83% identical), Y_RNA (83% identical), Y_RNA (82% identical), and 98 more.